RNU6-1144P (RNA, U6 small nuclear 1144, pseudogene)
Gene: Small nuclear RNA gene on chromosome 6 (108,292,766 to 108,292,869, forward strand). Ensembl gene ENSG00000206974.
Homologues: Orthologues: chimpanzee U6 (100% identical), macaque U6 (93% identical), rat LOC120102581 (79% identical), mouse Gm23625 (78% identical). Paralogues in human: RNU6-16P (90% identical), RNU6-1 (89% identical), RNU6-15P (89% identical), RNU6-2 (89% identical), RNU6-393P (89% identical), RNU6-39P (89% identical), RNU6-3P (89% identical), RNU6-4P (89% identical), RNU6-5P (89% identical), RNU6-6P (89% identical), RNU6-9 (89% identical), RNU6-10P (88% identical), and 1286 more.